MMP9 (matrix metallopeptidase 9)
Diseases named in the same sentence as MMP9 in open-access papers (continued):
Sharing a sentence is not in itself a finding about the gene and the disease.
breast carcinoma (continued). "In breast carcinoma cells, the elevated expression of MMP9 correlated with the presence of H3K4me3 methylation." (PMID 34943943, 2021). "It has been demonstrated that vasodilator-stimulated phosphoprotein (VASP), MMP2, and MMP9 expression in breast cancer is diminished upon repression of STAT3 phosphorylation." (PMID 34488773, 2021). "In turn, CPTAC data suggest the downregulation of MMP-9 in breast cancer patients and upregulation of KRT19 (CK19)." (PMID 34884588, 2021). "Calycosin treatment downregulated expression levels of EMT- and metastasis-related proteins such as N-cadherin, Vimentin, CD147, MMP-2, and MMP-9 levels in breast cancer cells." (PMID 34096887, 2021). "In this presented study, we have demonstrated that HO-1 induced by nicardipine exerts antitumor effects by inhibiting cell motility via suppressing the MMP-9 expression in breast cancer cells." (PMID 34483918, 2021). "MMP-9, p-IκBα, and NF-κB (p65) have a certain relationship with the invasion and metastasis of breast cancer, and further study is needed to find out the pathway(s) through which they work." (PMID 33854560, 2021). "It is in line with our results as MMP-9 downregulation reduced the migration potential of breast cancer cells of different aggressiveness." (PMID 34884588, 2021). "We revealed that the expression of MMP-9 is significantly lower among breast cancer cohorts compared to normal tissue." (PMID 34884588, 2021). "MMP-9 and MMP-2 are implicated in the metastasis of breast cancers via degradation of the ECM and promotion of tumor vascularisation." (PMID 33968759, 2021). "Some of the most frequently observed MMPs is MMP9, which plays a significant role in breast cancer tumor colonization, metastasis, and epithelial-to-mesenchymal transition." (PMID 34221232, 2021). "Sera from patients with lung and breast cancer were analyzed by bidimensional zymography to detect the activity of MMP-9 and MMP-2." (PMID 35723387, 2021). "FGF1 increases matrix metalloproteinase-9 (MMP-9) in ENU1564 breast cancer via activating PI3K/AKT pathway, eventually promoting cancer metastasis." (PMID 33964962, 2021). "According to the Oncomine database, the MMP-9 expression was significantly elevated in breast cancer." (PMID 34181339, 2021). "In our previous study, we found that CDKN1A/p21 was upregulated under TNF-α and served as a positive regulator of TNF-α-induced MMP9 gene expression in breast cancer cells." (PMID 33572115, 2021). "The combination of HSP70‐inhibition and p‐Akt/MMP‐9 downregulation augmented the potency of the NP in breast cancer therapy." (PMID 33898169, 2021). "Recently, one study demonstrated that M2-like macrophages have been found to secrete large amounts of MMP-9 that promoted tumor progression both in breast cancer and in colon cancer, which was considered as prognostic markers and therapeutic targets." (PMID 34717710, 2021). "We previously reported that NA elevated breast cancer cell infiltration via adrenergic receptors and upregulated MMP9 expression, which contributes to extracellular matrix degradation in MDA-MB-231 cells." (PMID 33633796, 2021). "Our previous studies showed that the treatment of breast cancer cells with TNF-α resulted in upregulation of CDKN1A/p21-dependent MMP9 expression/secretion which was found to be essential for cell migration." (PMID 33572115, 2021). "Validation of PTs in TCGA and GTEx samples using GEPIA demonstrated that the mRNA expression of MMP9 was significantly higher in breast cancer tissues than in normal tissues." (PMID 34335799, 2021). "For instance, in MCF-7 breast cancer cells, activation of Axl stimulated NF-κB mediated activation of matrix metalloproteinase-9 (MMP9)." (PMID 33806258, 2021). "These bioinformatics analyses identified MMP-9 as a potential marker to be developed as a specific target for breast cancer therapy." (PMID 34181339, 2021).
breast carcinoma (continued). "Patients undergoing primary breast cancer surgery who received propofol/paravertebral anesthesia had less elevated MMP-3 and MMP-9 as compared with those who received sevoflurane based anesthesia during primary breast cancer surgery." (PMID 35127500, 2021). "Ablation of CXCR4 in breast cancer cells was further shown to inhibit bone metastasis in a mouse model by attenuating the PI3K/AKT/matrix metallopeptidase 9 (MMP9) axis." (PMID 34064589, 2021). "Previous studies have found that celastrol also had the ability to down-regulate NF-κB-mediated MMP-9 level in breast cancer cells and fibroblast-like synoviocytes in rheumatoid arthritis." (PMID 34182541, 2021). "It is reported that MT2A promotes the migration and invasiveness of cancer cells in breast cancer and mucoepidermoid cancer by regulating MMP9 expression." (PMID 34572779, 2021). "DNA promoter methylation is important for the regulation of MMP9 expression, and H3K4me3 is high in the promoter DNA regions, showing the importance of these binding sites in MMP9 transcription in breast cancer cell lines." (PMID 34943943, 2021). "The catalytic end products of HO-1 consequently result in MMP-9 inhibition and cell migration in breast cancer cells." (PMID 34483918, 2021). "In particular, the transcriptional induction of integrin β1 expression mediated by the nuclear SIPA1 led to the activation of the FAK/PI3K/Akt transduction pathway, which in turn enhanced MMP9 expression together with breast cancer cell invasion." (PMID 33562737, 2021). "Our results revealed that ATQ reduced the constitutive expression of vimentin and MMP-9 suggesting ATQ inhibits metastatic markers in breast cancer." (PMID 34071408, 2021). "High expression of MMP9 is often found in breast cancer 32; in malignant breast cancer tissues, MMP9 shows strong positive expression." (PMID 33854593, 2021). "Among different MMPs, MMP-2 (gelatinase-A) and MMP-9 (gelatinase-B) are strongly expressed and correlated with the tumor invasion and metastasis in breast cancer cells." (PMID 34483918, 2021). "Significant MMP-9 overexpression characterizes the triple-negative MDA-MB-231 breast cancer cell line." (PMID 34884588, 2021). "Regarding breast cancer, mPRα and MMP9 expression and Akt phosphorylation have been reported to be higher in breast cancer tissue compared to non-cancerous one." (PMID 34831222, 2021). "Overexpression of MMP9 can enhance the colony formation and migration ability of breast cancer cells, whereas inhibition of MMP9 leads to a significant decrease in invasive ability." (PMID 33854593, 2021). "Further mechanistic study revealed that PRMT7 promoted breast cancer cell invasion by regulating MMP9 (matrix metalloproteinase 9) which is a famous mediator of breast cancer metastasis." (PMID 34712331, 2021). "This herbal medicine (at 40%) inhibits the growth and invasion of breast cancer by inducing cell cycle arrest and reducing MMP9 and EMT." (PMID 34200897, 2021). "In our recent work, we demonstrated that MMP9 is directly involved in TNF-α-induced breast cancer cell migration." (PMID 33572115, 2021). "Future studies of the effect of tangeretin on MMP9 activity in metastatic breast cancer are warranted." (PMID 34335799, 2021). "Conversely, TGFβ1 treatment decreased E-cadherin levels and increased N-cadherin, Vimentin, CD147, MMP2 and MMP9 expression levels in the breast cancer cells." (PMID 34096887, 2021). "Activation of the PI3K/PTEN/AKT/mTOR pathway promotes invasion and metastasis by increasing the expression of MMP9 in hepatocellular carcinoma cells and human breast cancer cells." (PMID 34335799, 2021). "Because of the relatively high expression of MMP9 in patients with high invasive breast cancer, it is of great clinical significance to study the regulation mechanism of MMP9 expression." (PMID 33430865, 2021). "ITGB1 was associated with EMT of breast cancer and the ITGB1/FAK/Src/AKT/β-catenin/MMP-9 signaling axis was an important signaling pathway." (PMID 33796128, 2021).
breast carcinoma (continued). "Myofibroblasts and adipocytes are major sources of matrix metalloproteinases, for example, MMP-2 and MMP-9, two MMPs receiving attention in research focusing on breast cancer progression." (PMID 34944905, 2021). "Our work shows that TIMELESS can inhibit the invasion and metastasis of breast cancer cells by decreasing the expression of MMP9." (PMID 33430865, 2021). "On the other hand, BMAL1 overexpression of Matrix Metalloprotein 9 (MMP9) up-regulates the expression of inflammatory factors that promotes breast cancer cell invasiveness and metastasis." (PMID 35126099, 2021). "In this study, DACH1 inhibited the invasion and metastasis of breast cancer cells by decreasing MMP9 expression." (PMID 34772908, 2021). "S1P enhances invasion and migration of breast cancer cells both in vitro and in vivo by inducing the expression of matrix metalloproteinase-9 (MMP-9) in the S1P/S1PR3/Gαq axis." (PMID 35201458, 2021). "The compounds that were suggested as responsible for the MMP9 inhibition as well as breast cancer cytotoxicities were oxytetracycline (OTC), with IC50 18.69 μM and 414.20 μM, respectively." (PMID 33800366, 2021). "In our study, TIMELESS inhibited the invasion and metastasis of breast cancer cells by down-regulating the mRNA and protein levels of MMP9." (PMID 33430865, 2021). "Our data suggested that tRF-17-79MP9PP inhibits the THBS1-mediated TGF-β1/Smad3 pathway and the EMT related genes (MMP3, MMP-9 and N-cadherin) in breast cancer cells." (PMID 33912465, 2021). "UDP released by the doxorubicin treated breast cancer cells, upregulates the expression as well as the enzymatic effect of MMP9 via P2Y6 mediated activation of MAPK and NF-κB signaling." (PMID 34588926, 2021). "MMP1 and MMP9 can be used as independent prognostic factors to predict the prognosis of breast cancer patients, in order to further study the pathological mechanism and possible treatment targets for breast cancer, especially for Her2 and Basel subtypes." (PMID 35069702, 2021). "Such UDP-induced effect of MMP9 was found to promote metastasis of breast cancer cells in both the in vitro and in vivo models of breast cancer." (PMID 34588926, 2021). "Our previous study found that the perilla leaves extract, which mainly contains RA and other polyphenols, strongly inhibits invasion and migration via diminished MMP-9 secretion and activity in breast cancer cells." (PMID 34439757, 2021). "The administration of ISL alone to xenograft animals significantly inhibits lung metastasis in breast cancer and suppresses the expression of matrix metallopeptidase-9/7/2 (MMP-9/7/2), NF-κB, and cyclooxygenase-2 (COX-2)." (PMID 33401375, 2021). "The validation of target genes by using ONCOMINE showed that, in samples from a TCGA study, the mRNA level of MMP9 was significantly higher in metastatic breast cancer cells than in normal breast cells with p=2.97 × 10−16." (PMID 34335799, 2021). "An example of the role exerted by MMPs in breast cancer is the MMP-9-dependent enhancement of breast cancer malignancy through activation of the TGF-β/SMAD signaling." (PMID 33946660, 2021). "HMOX1 suppress breast cancer invasion through inhibiting the expression of matrixmetalloproteinase-9 (MMP9)." (PMID 34109210, 2021). "In order to confirm the involvement of HO-1 in mediating MMP-9 expression affected by nicardipine, breast cancer cells were subjected to HO-1 inhibition by SnPP and ZnPP." (PMID 34483918, 2021). "In vitro studies and analysis of available data on breast cancer patients presented in this paper indicate high levels of MMP-9 in breast tumors." (PMID 34884588, 2021). "Similar results were obtained in the examination of MMP9 protein level in breast cancer cells, that is, the overexpression of TIMELESS increased the expression of endogenous MMP9, while TIMELESS knockdown inhibited the protein level of MMP9." (PMID 33430865, 2021).
breast carcinoma (continued). "MMP9 is upregulated in breast cancer cells compared with normal tissue and is correlated with metastasis and recurrence in breast cancer." (PMID 34335799, 2021). "TGFβRI SUMOylation regulates TGFβ-MMP9 cascade and inhibits anchorage-independence growth, proliferation, migration and invasion in breast cancer cells." (PMID 33968766, 2021). "Our findings confirmed the expression of MMP9 in the human breast cancer brain metastasis samples by IHC staining." (PMID 34421353, 2021). "IL-1β is also linked to the migration and invasion in breast cancer, for example through loss of E-cadherin and an increase in MMP-2 and MMP-9, leading to a degradation of the extracellular matrix." (PMID 34944905, 2021). "Our research team has been intensively studying the diagnostic usefulness of MMPs in gynaecological cancers, including MMP-2 and MMP-9 in breast cancer." (PMID 33916127, 2021). "Expression of MMP-9 in human breast cancer cells and cell migration have been shown to be induced by the Ca2+/CaM-binding protein TBC1D3, and these effects were enhanced upon Ca2+/CaM binding to this protein, as it prevented its ubiquitination and degradation." (PMID 31991573, 2020). "Recent study indicates that disruption of the interaction of Hsp90 and MMP‐2 and MMP‐9 results in metastasis suppression in breast cancer." (PMID 32180962, 2020). "Increased MMP9 expression correlates with aggressive breast cancer with higher incidence of relapse and metastasis." (PMID 33119681, 2020). "Previous studies have demonstrated the expression and activity of MMP-9 in a variety of human cancer cells, including breast cancer cells." (PMID 31893611, 2020). "MMP-2 and MMP-9 secreted by astrocytes are found responsible for facilitating lung and breast cancer brain metastasis progression, presumably by making the EMC more favorable for tumor cells." (PMID 33262947, 2020). "Blocking of the interaction of HSP90 and MMP-2 and MMP-9 induces metastasis suppression in breast cancer and lung cancer, respectively." (PMID 32961679, 2020). "Among them, the metalloproteinases MMP2 and MMP9 that play a key role in the degradation of type IV collagen are overexpressed in breast cancer and correlate with poor prognosis of patients." (PMID 32226772, 2020). "The loss of CPEB1 results in poly(A) tail lengthening and increased translation of the mRNA for MMP9 in breast cancer cells." (PMID 32967226, 2020). "Using TA3 murine mammary carcinoma cells, Yu and Stamenkovic showed that MMP9 is localized on the cell surface in a CD44-dependent manner and stimulates proteolytic cleavage of TGF-β, and they proposed a novel role for MMP9 in TGF-β-dependent tumorigenesis." (PMID 33172999, 2020). "Luteolin decreased cell viability in breast cancer cells as well as inhibited migration and invasion by decreasing the expression of matrix metalloproteinase-9 (MMP9)." (PMID 32708138, 2020). "Collectively, these results suggest that IL-22 enhances the invasive capacity of breast cancer cells via the induction of MMP9 expression, as well as via S1P signaling." (PMID 31935914, 2020). "This study aims to select local plants in our state, as anti-breast cancer agent with hemopexin-like domain of MMP9 (PEX9) as the selective protein target." (PMID 33066411, 2020). "Our results showed that it decreased the release of pro-inflammatory and pro-angiogenic cytokines (IL-6 and IL-8) and MMP-9, which are regarded as factors for breast cancer cell invasion and stimulation of angiogenesis." (PMID 33260615, 2020). "The intracellular domain of CD44 can act as a co-transcription factor for RUNX2, inducing MMP-9 expression in breast carcinoma cells." (PMID 32204402, 2020). "In the present study, three EMT-related proteins E-cad, N-cad, and vimentin and two proteolytic enzymes MMP-2 and MMP-9 were selected as targets to investigate the influence of SA in the indicated breast cancer cells." (PMID 33381039, 2020).
breast carcinoma (continued). "In contrast, others reported that MMP9 is produced by human breast cancer cells and is required for pulmonary metastasis in a mouse orthotopic model of basal-like breast cancer." (PMID 33119681, 2020). "Here, the spatiotemporal organization and dynamics of specialized lipids surrounding the PIP2-mediated signaling pathway at fusing secretory vesicles containing the pro-tumor marker, MMP-9 was investigated in living MCF-7 breast cancer cells." (PMID 32829709, 2020). "Initially, HspB1 was reported to promote the invasion of breast cancer cells by upregulation of MMP-9 expression but decrease the motility of breast cancer cells." (PMID 32927696, 2020). "Matrix metalloproteinases (MMPs) such as MMP2, MMP7, and MMP9 are metastasis markers in breast cancer." (PMID 32408199, 2020). "In this regard, in vitro studies have revealed that cancer cells induce stromal fibroblasts to express MMPs (i.e., MMP-9), demonstrating the complex tumor-stromal crosstalk that occurs in breast cancer." (PMID 32384738, 2020). "The addition of CXCL13 to breast cancer cells in vitro increased expression of matrix metalloproteinase-9 (MMP-9) and genes reasonable for driving the epithelial to mesenchymal transition (EMT)." (PMID 33193299, 2020). "In this context, we would like to refer to our previously published article evaluating GTPase Rho A and MMP-9 as potential biomarkers, individually and in set, in breast cancer prediction." (PMID 32839667, 2020). "Another protein that plays a significant role in cancer cell migration is matrix metalloprotease 9 (MMP-9), the higher expression of which correlates with breast cancer metastasis." (PMID 32806551, 2020). "In a follow-up study looking at molecular regulators of extravasation, the same group found that in addition to ICAM-1, MMP-9 and frizzled 4 were found to regulate invasion of bone-metastatic breast cancer cells." (PMID 31936342, 2020). "IL-6, IL-8, and MMP-9 belong to the group of factors that participate in breast cancer cell invasion and adhesion." (PMID 33260615, 2020). "MMP-2 or (and) MMP-9 was downregulated in breast cancer, osteosarcoma, and renal carcinoma cells with the silence of HMGN5." (PMID 32596388, 2020). "CM from both breast cancer cell lines increased the expression of both transcripts, and ezrin depletion inhibited the stimulus-dependent expression of MMP9 mRNA in both cell lines, and VEGFA mRNA expression in MCF-7 cells." (PMID 33086476, 2020). "STAT3 signaling pathway plays a crucial role in proliferation (Bcl-2, Survivin), angiogenesis (HIF1α, VEGF), and epithelial-mesenchymal transition (Vimentin, MMP-9) in breast cancer cells and has been validated as a drug target for cancer therapy." (PMID 31948057, 2020). "At the same time, the expressions of MMP2 and MMP9 proteins in trinegative breast cancer cells treated with Bicalutamide were significantly decreased, and the expression of AR protein was also significantly decreased." (PMID 32332626, 2020). "Chemotherapy-resistant breast cancer cell-derived factors selectively enhance neutrophil survival and secretion of MMP9." (PMID 33049964, 2020). "Addition of S1P induced activation of matrix metalloproteinase-9 (MMP-9), which is known to increase invasion in breast cancer cells." (PMID 32977496, 2020). "Albrengues and colleagues found that laminin-111 digestion by neutrophil-derived matrix metalloproteinase-9 (MMP9) and elastase reveals cryptic sites that in turn activate β1-integrin signaling to re-awaken dormant breast cancer cells in the lung." (PMID 33014869, 2020). "Relevantly, EVs derived from 8701-BC breast cancer cells and HT-1080 fibrosarcoma cells were reported to contain MMP9 in both pro- and mature forms with proteolytic activity." (PMID 32260433, 2020). "For instance, miR-509 was shown to be downregulated in brain metastases and promotes breast cancer cell invasion by upregulating RhoC/MMP9 and TNFα." (PMID 33002044, 2020).